SNHG6 (small nucleolar RNA host gene 6)
Diseases named in the same sentence as SNHG6 in open-access papers (continued):
Sharing a sentence is not in itself a finding about the gene and the disease.
COVID-19 (1 paper, 2021). A disease caused by infection with severe acute respiratory syndrome coronavirus 2. "The observed down-regulation of SNHG6 in the peripheral blood of COVID-19 patients might be due to a regulatory feedback loop between this lncRNA and TGF-β." (PMID 34147082, 2021). "Finally, the diagnostic power of VDR, CYP27B and SNHG6, SNHG16, Linc00511 and Linc00346 has been appraised in distinguishing COVID-19 patients from healthy controls and in distinguishing ICU-hospitalized patients from the other group of patients." (PMID 34147082, 2021). "We reported lower expressions of SNHG6 and SNHG16 in COVID-19 patients of both sexes compared with sex-matched controls." (PMID 34147082, 2021).
depression (1 paper, 2024). "Meanwhile, lncRNA SNHG6 is elevated along with the depression-like behaviors in mice, and lncRNA SNHG6 knockdown alleviates the depression-like behavior." (PMID 39058106, 2024).
Hodgkins lymphoma (1 paper, 2022). A heterogeneous group of malignant lymphoid neoplasms of B-cell origin characterized histologically by the presence of Hodgkin and Reed-Sternberg (HRS) cells in the vast majority of cases. "In a recent study analyzing lncRNA-mediated ceRNA networks in Hodgkin lymphoma, SNHG6 was reported as upregulated, and highly associated with patients’ relapse." (PMID 35740344, 2022).
leukemia (1 paper, 2024). A malignant (clonal) hematologic disorder, involving hematopoietic stem cells and characterized by the presence of primitive or atypical myeloid or lymphoid cells in the bone marrow and the blood. "In this respect, our cell-based and transcriptomic analyses predicted a role for SNHG6 in hematopoiesis and leukemia." (PMID 38419051, 2024). "SNHG6 KD reduced the proliferation of leukemia cells and sensitized them to differentiation." (PMID 38419051, 2024). "Finally, we established a mouse K562 leukemia xenograft model to determine whether SNHG6 KD attenuates tumor growth in vivo." (PMID 38419051, 2024).
nasopharyngeal carcinoma (1 paper, 2023). A carcinoma arising from the nasopharyngeal epithelium. "Moreover, ARPP19 overexpression was corroborated to neutralize the repressive effect of SNHG6 knockdown on the progression of nasopharyngeal carcinoma." (PMID 36874625, 2023).
pancreatic cancer (1 paper, 2023). "Researchers observed that lower levels of SNHG6 are linked with GEM-resistant pancreatic cancer and that higher SNHG6 levels are associated with better patient survival rates." (PMID 37735423, 2023). "The study concludes that manipulating the SNHG6/miR-944/KPNA5 pathway could be a viable strategy for overcoming GEM resistance in pancreatic cancer, thereby potentially improving patient outcomes." (PMID 37735423, 2023).
rectal cancer (1 paper, 2021). A primary or metastatic malignant neoplasm that affects the rectum. "Another work showed that lncRNA small nucleolar RNA host gene 6 (SNHG6) expressed a high expression level in rectal cancer and correlated with shorter overall survival time." (PMID 34249085, 2021).
thyroid cancer (1 paper, 2025). "Compared to normal thyroid cells (Nthy-ori-3-1), SNHG6 was also highly expressed in thyroid cancer cell lines K1 and TPC1." (PMID 41234719, 2025). "Functional experiments demonstrated that interfering with SNHG6 significantly inhibited thyroid cancer cell proliferation, while SNHG6 overexpression enhanced cellular proliferation capacity." (PMID 41234719, 2025).
tumor (59 papers, 2019 to 2026). "SNHG6 upregulation in hepatic cellular carcinoma (HCC) is reported to have an association with tumor growth and metastasis." (PMID 37735423, 2023). "SNHG6 is a notable lncRNA, observed to be overexpressed in various cancer types; its perturbation has been linked to tumor progression, emphasizing its significance in oncogenesis." (PMID 37735423, 2023). "A strong association between SNHG6 upregulated expression and advanced tumor stages in CRC is reported." (PMID 37735423, 2023). "Elevated SNHG6 expression in RCC specimens were markedly associated with RCC tumour burden and lymph node infiltration." (PMID 33968736, 2021). "The pooled data revealed that increased expression of SNHG6 was significantly associated with tumor invasion depth, LNM, DM, and advanced TNM stage, indicating that evaluated SNHG6 expression correlated with advanced clinicopathological characteristics." (PMID 32321469, 2020). "We found that increased expression of SNHG6 was associated with pathological stage and lymph node infiltration, and acted as an independent prognostic factor of tumor recurrence in patients with NSCLC." (PMID 32147945, 2020). "In summary, our findings demonstrated that upregulation of SNHG6 expression was associated with pathological stage and lymph node infiltration and acted as an independent prognostic factor of tumor recurrence in LAC patients." (PMID 32147945, 2020). "Univariate Cox regression analysis indicated that high SNHG6 expression was related to an increased risk of poor survival and tumor recurrence in NSCLC." (PMID 32147945, 2020). "Li and his colleagues found that increased expression of SNHG6 was associated with pathological stage and lymph node infiltration, and acted as an independent prognostic factor of tumor recurrence in patients with NSCLC." (PMID 32518528, 2020). "Increased expression levels of SNHG6 are associated with tumour progression and are inversely correlated with prognosis." (PMID 31119871, 2019). "Taken together, SNHG6 may be implicated in the regulation of tumor development by multiple pathways and is considered a poor prognostic biomarker for human cancers." (PMID 37004005, 2023). "Abnormal expression of lncRNA Snhg6 is seen in pediatric tumors, including Wilms tumor, gliomas, osteosarcoma, and liver cancers, which is associated with sustained tumor growth and metastases." (PMID 37345170, 2023). "Collectively, SNHG6 deficiency hindered GC tumor growth in vivo." (PMID 34821362, 2021). "In PCa, elevated expression of SNHG6 in tumour tissues was speculated to be associated with an unfavourable prognosis." (PMID 33968736, 2021). "The high expression level of SNHG6 is associated with tumor progression and poor prognosis." (PMID 32518528, 2020). "Herein, we found that increased expression of SNHG6 or decreased expression of miR‐101‐3p was associated with pathological stage and lymph node infiltration and acted as an independent prognostic factor of tumor recurrence in patients with NSCLC." (PMID 32147945, 2020). "Consistent with a previous study, we found that SNHG6 expression was increased and associated with poor prognosis, pathological stage and lymph node infiltration, acting as an independent prognostic factor of tumor recurrence in patients with NSCLC." (PMID 32147945, 2020). "High expression of SNHG6 was associated with tumor progression and poor survival." (PMID 30626446, 2019). "Moreover, elevated SNHG6 expression was positively associated with tumor invasion depth (OR = 1.76, 95% CI: 1.18–2.63), LNM (OR = 1.60, 95% CI: 1.18–2.17), DM (OR = 1.90, 95% CI: 1.37–2.64) and advanced TNM stage (OR = 1.88, 95% CI: 1.36–2.60) in patients with cancers." (PMID 32321469, 2020). "Knocking down SNHG6 suppresses macrophage M2 polarization, endoplasmic reticulum stress, and tumor growth—both in vitro and in vivo—and also boosts the anti‐tumor efficacy of anti‐PD‐1 therapy." (PMID 41474641, 2026).
tumor (continued). "In vivo data further support the potential of SNHG6 knockdown to suppress tumor growth, highlighting its viability as a therapeutic target." (PMID 41301542, 2025). "SNHG6 correlates with tumor stage and metastasis as a prognostic marker, and SNHG22 promotes cell proliferation and invasion through the miR-128-3p/E2F3 axis." (PMID 41301542, 2025). "Consistent with the observed effect on tumor volume, the overall weight of SNHG6-KD tumors was also significantly lower than that in control tumors." (PMID 38419051, 2024). "SNHG6 is involved in different tumor hallmarks including increased cell proliferation, evasion of apoptosis, metastasis, and invasion." (PMID 37735423, 2023). "In vivo knockdown of SNHG6 in BALB/c nude mice induced cell cycle arrest and caused a reduction in tumor weight and volume." (PMID 37735423, 2023). "SNHG6 suppression via miRNA brought about tumor proliferation inhibition, cell cycle progression arrest at the G0 phase, cell migration and invasion inhibition, and apoptosis." (PMID 37735423, 2023). "Essentially, SNHG6 "sponges" or pairs with complementary sequences in these tumor suppressor miRNAs." (PMID 37735423, 2023). "PNS repressed SNHG6 expression while simultaneously triggering the expression of miR-137 which being tumor-suppressor miRNA inhibits cell proliferation and induces apoptosis." (PMID 37735423, 2023). "Uncontrolled SNHG6 expression enhances the process of angiogenesis, tumor migration, invasion, metastasis, epithelial–mesenchymal transition (EMT), and chemoresistance while interrupting the malignant cell cycle and diminishing apoptosis." (PMID 37735423, 2023). "The overexpression of SNHG6 has been observed in many cancers, the increased expression is related to poor prognosis, tumor progression, and decreased survival rate." (PMID 37735423, 2023). "Recently, SNHG6 is found to influence tumor malignancy through multiple pathways, such as sponge miRNAs, directly interacting with target genes or signaling pathways." (PMID 37005451, 2023). "By acting as a sponge for tumor-suppressor microRNAs, SNHG6 prevents apoptosis and promotes epithelial-to-mesenchymal transition (EMT) characteristics." (PMID 37735423, 2023). "Similar to SNHG16, SNHG6 regulates gene expression transcriptionally by recruiting EZH2 to promoter regions of different tumor suppressor genes, such as P27 and P21, and represses their expression through methylation of their promoters." (PMID 35740344, 2022). "Since SNHG6 is itself elevated in tamoxifen resistant cells, the miRNAs that it sponges are expected to be tumor-suppressive." (PMID 36212408, 2022). "Analyzed expression data demonstrated that tumor grade progression of studied patients and higher expression levels of SNHG6 RNA in their tumors were concurrent." (PMID 35096086, 2022). "SNHG6 expression level measurement demonstrated that patients over 60 showed higher expression levels of SNHG6 in their tumor tissues compared to the patients aged 60 or younger." (PMID 35096086, 2022). "LncRNAs regulate EMT process by targeting EMT-related signalling pathways directly (i.e., H19, HOTAIR, ZEB2-AS1, LincRNA-p21 and SNHG1), or function as ceRNAs (i.e., H19, HOTTIP, MALAT1, SNHG1 and SNHG6) for tumour suppressive miRNAs." (PMID 36310592, 2022). "In NSCLC, high expression of SNHG6 was negatively correlated with miR-944 and was significantly associated with later TNM stage, larger tumor size, and shorter OS." (PMID 36077769, 2022). "SNHG6 silencing restrained tumor growth in vivo and suppressed the expressions of cell cycle-related proteins in the G1/S transition." (PMID 36494339, 2022). "High expression of SNHG6 has been demonstrated to correlate with tumor progression and poor prognosis in multiple human cancers." (PMID 36212408, 2022). "Suppressed SNHG6 also resulted in lower tumor weights and volumes in xenograft mouse models, thus supporting our findings." (PMID 34771513, 2021).
tumor (continued). "In this study, we found that in mouse of Lewis lung cancer xenograft, long non-coding RNA Snhg6 (lncRNA Snhg6) was highly expressed in tumor-derived MDSCs compared with spleen-derived MDSCs." (PMID 34794493, 2021). "In summary, these evidences manifested that the repression of KLF6 was indispensable for the tumor-promoting effect of SNHG6." (PMID 33431838, 2021). "SNHG6 knockdown significantly reduced the tumor growth, and the tumor volume plus tumor weight were much smaller than the control mice." (PMID 33431838, 2021). "SNHG6 has a role in cell apoptosis, invasion, proliferation, and migration in vitro, and enhanced tumor growth in vivo, but the role of SNHG6 in CCA remains uncertain." (PMID 34095461, 2021). "Fan’s and Zhang’s groups both found that SNHG6 expression is significantly increased in ESCC tissues and is associated with tumor size and TNM stage." (PMID 32518528, 2020). "SNHG6 exerts its function mainly by serving as miRNA sponge to antagonize the connections between multiple tumor suppressor miRNAs and their target mRNAs19-23." (PMID 32226515, 2020). "In conclusion, this meta-analysis demonstrated that SNHG6 overexpression is correlated with shorter overall survival, as well as tumor invasion depth, lymph node metastasis, distant metastasis, and advanced TNM stage." (PMID 32321469, 2020). "Upregulated SNHG6 arrests tumor cell cycle and reduces apoptosis but promotes migration, invasion, metastasis, epithelial-mesenchymal transition (EMT), and chemoresistance in tumors." (PMID 32518528, 2020). "What's more, upregulated SNHG6 is related to advanced tumor progression and short survival in these tumor patients." (PMID 32226515, 2020). "Three studies involving 228 patients elucidated the link between SNHG6 expression and tumor invasion depth (≥T2 vs T1)." (PMID 32000704, 2020). "This review will summarize the most recent findings on SNHG6, focusing on the effect of its upregulation and its role as ceRNA in tumor progression." (PMID 32518528, 2020). "Recent studies have confirmed our conclusion: E2F7 has been proven to overexpressed in LUAD, and its expression is regulated by SNHG6 through the competitive sponging of miR-26a-5p, which promotes tumor growth and metastasis." (PMID 33042838, 2020). "SNHG6 is responsible for cell proliferation, migration, invasion, reduced apoptosis in vitro, increased tumor size, and increased metastases in vivo." (PMID 32518528, 2020). "Functionally, SNHG6 participates in cell proliferation, migration, invasion and apoptosis in vitro, and promoted tumor growth in vivo." (PMID 32226515, 2020). "Kaplan‐Meier analysis demonstrated that the patients with high SNHG6 expression displayed a poorer survival and a higher tumor recurrence as compared with those with low SNHG6 expression." (PMID 32147945, 2020). "According to the results, SNHG6 knockdown inhibited tumor growth compared with control cells, as proven previously." (PMID 31516391, 2019). "Statistical analysis demonstrated that SNHG6 expression was correlated with tumor invasion depth (P = 0.010), distant metastasis (P = 0.001), lymph node metastasis (P = 0.013), and TNM stage (P = 0.008)." (PMID 30626446, 2019). "Taken together, these results indicate that SNHG6 promotes tumor growth and metastasis in vivo, which is consistent with its functions in vitro." (PMID 30626446, 2019). "During our research, we found that nucleolar RNA host gene 6 (SNHG6) was over-expressed in primary tumor samples and OS cell lines (SOSP-9607 and MG63)." (PMID 30988663, 2019). "Using a xenograft mouse model, we demonstrate that SNHG6 KD attenuated tumor growth in vivo." (PMID 38419051, 2024). "and high SNHG6 expression is correlated with tumour progression and poor prognosis." (PMID 38253617, 2024).
tumor (continued). "Whereas, it is still unclear whether SNHG6 has a place in the tumor microenvironment of KIRP as well." (PMID 37004005, 2023). "SNHG6 has been previously suggested to be the candidate new anti-tumor therapeutic target." (PMID 37005451, 2023). "Therefore, the oncogenic or tumor-suppressing role of SNHG6 can only be determined by further investigation of its downstream pathways." (PMID 37735423, 2023). "SNHG6 predominantly acts as a ceRNA counteracting various tumor suppressor miRNAs." (PMID 37735423, 2023). "SNHG6 knockdown in xenografted mice led to a reduction in tumor volume." (PMID 37735423, 2023). "The research found that both SNHG6 and Yes-associated protein 1 (YAP1) were significantly upregulated in ovarian cancer tissues compared to adjacent normal tissues, while the expression of miR-543, a known tumor suppressor, was substantially reduced." (PMID 37735423, 2023). "Interestingly, lower macrophage abundance in the tumor microenvironment under high expression state of SNHG6 led to a deterioration of OS in KIRP patients." (PMID 37004005, 2023). "As a result, the pro-oncogenic effect of SNHG6 on KIRP may be partially related to tumor-infiltrating immune cells, especially macrophages and cancer associated fibroblasts." (PMID 37004005, 2023). "The experiments on nude mice also suggested that SNHG6 regulated tumor growth in vivo." (PMID 36494339, 2022). "SNHG6 was more expressed in CRC tumors than non-tumor tissues." (PMID 35096086, 2022). "In tumor tissues, SNHG6 upregulation and tumors’ grade progression were concurrent." (PMID 35096086, 2022). "Also, we performed the xenograft assay to investigate the function of SNHG6 during the tumor growth in vivo." (PMID 33663502, 2021). "Impairment of SNHG6 reduced tumour cell viability and mobility and stimulated apoptosis." (PMID 33968736, 2021). "In our present study, we identified that SP1 modulated the transcription of SNHG6, which demonstrated that SP1 could regulate the expression of tumor-associated proteins indirectly via lncRNAs." (PMID 33431838, 2021). "Several studies have investigated the tumor-promoting function of SNHG6 in the various tumors." (PMID 33431838, 2021). "Results shown that down-regulation of SNHG6 led to significantly decreased tumor volume." (PMID 33663502, 2021). "Finally, by the tumor growth assay using nude mice, we confirmed down-regulation of SNHG6 significantly reduced the tumor size by decreasing the proliferation ability in HCC tissues." (PMID 33663502, 2021). "Finally, we performed the tumor growth assay using stable down-regulated SNHG6 Huh7 cells, and decreased tumor volume indicated knockdown of SNHG6 inhibited HCC progression." (PMID 33663502, 2021). "Finally, we found that down-regulation of SNHG6 dramatically reduced the tumor growth ability of Huh7 cells in vivo." (PMID 33663502, 2021). "Overexpressed SNHG6 is tightly related to tumor development and poor survival." (PMID 32518528, 2020). "Upregulated SNHG6 relates to advanced tumor progression and short survival in patients." (PMID 32518528, 2020). "The role of SNHG6 in vivo was confirmed by xenograft tumor model." (PMID 32782439, 2020). "Furthermore, SNHG6 was identified as a tumor promoter targeting miR-26a-5p, as reduction of SNHG6 expression in OS cell lines was able to reduce cell viability and migration in vitro, arrest cell cycle at G0/G1 phase, induce cell apoptosis." (PMID 30988663, 2019). "However, knockdown of SNHG6 markedly reduced the increase in the tumour volumes in the xenograft mouse model." (PMID 31119871, 2019). "Furthermore, lncRNA Snhg6, which is highly expressed in tumor-derived myeloid-derived suppressor cells (MDSCs), promotes the differentiation of CD11b+ Ly6G− Ly6Chigh monocytic (M)-MDSCs by stabilizing EZH2 through the protein ubiquitination degradation pathway." (PMID 37345170, 2023).